NDRG1 (N-myc downstream regulated 1)
Diseases named in the same sentence as NDRG1 in open-access papers (continued):
Sharing a sentence is not in itself a finding about the gene and the disease.
cancer (continued). "In our recent studies, as well as those from others, it has been demonstrated that NDRG1 plays a key role in the regulation of cellular signaling via a variety of pathways inhibiting cancer cell invasion and migration." (PMID 26431493, 2015). "It is well established that intracellular iron levels regulate the expression of NDRG1, with iron-depletion markedly up-regulating NDRG1 at both the mRNA and protein levels in a variety of different cancer cell-types." (PMID 26125440, 2015). "When migration assay experiments were performed, it was shown that NDRG1 reduced cancer cell migration through inhibition of Src activation." (PMID 26431493, 2015). "The NDRG1 promoter is hypermethylated and repressed in many types of cancers and overexpression studies in multiple cell lines have demonstrated growth inhibitory effects both in vitro and in vivo." (PMID 26304929, 2015). "We previously discovered that NDRG1 plays a novel role in decreasing cancer cell migration by targeting the TGF-β-mediated EMT and ROCK/pMLC2 pathways." (PMID 25860930, 2015). "Recent studies have demonstrated that NDRG1 acts as a metastasis suppressor with its expression correlating with the inhibition of cancer progression in vivo and cancer cell migration and invasion in vitro." (PMID 25860930, 2015). "NDRG1 is a multifunctional protein involved in various aspects of carcinogenesis and the development of cancer, including cell proliferation, cell cycle regulation, cell differentiation, cancer metastasis and invasion." (PMID 24260043, 2013). "Human orthologs to NDL proteins and mouse NDRG1 are among the few well-documented metastasis suppressors and are being used as possible cancer therapeutics." (PMID 24223735, 2013). "A number of studies indicate that overexpression of NDRG1 in cancer cell lines generates conspicuous phenotypes." (PMID 23741453, 2013). "Notwithstanding the ubiquitous expression of NDRG1 in most cell types and its upregulation in numerous types of cancer, a definitive analysis of NDRG1’s function in vivo pointed to a role limited to myelin sheath maintenance and regeneration." (PMID 24066183, 2013). "It has been suggested that the phosphorylation of NDRG1 inhibits the malignant progression of cancer by suppressing the activity of the NF-κB (nuclear factor-κB) signalling pathway, thereby reducing the expression of angiogenic CXC chemokines." (PMID 23634903, 2013). "Presumably, NDRG1 participates in angiogenesis, metastasis, and mechanisms leading to anti-cancer drug resistance." (PMID 23130941, 2012). "It seems less likely that β-catenin plays a pivotal role in suppression of metastasis by NDRG1 knockdown in highly metastatic cancer cells." (PMID 22844455, 2012). "NDRG1 is expressed at low levels in normal tissues but its expression is increased in a variety of cancers, making it an important cancer marker." (PMID 21455298, 2011). "If indeed NDRG1 is a potential tumour suppressor protein, it would be a survival advantage for an aggressive cancer to shut down the ability to upregulate a growth inhibitory protein." (PMID 16832411, 2006). "N-myc downstream-regulated gene-1 (NDRG1) is a recently described hypoxia-inducible protein that is upregulated in various human cancers." (PMID 16832411, 2006). "As seen from the table, differential expression between normal and cancer tissues was much more apparent in Ndrg1 than HIF-1α." (PMID 15341671, 2004). "Our work in several human tissues showed that in the majority of these organs Ndrg1 protein was differentially overexpressed in cancers compared to normal tissues." (PMID 15341671, 2004). "Several normal tissue samples showed some Ndrg1 expression albeit at lower levels than in cancer samples of similar tissues." (PMID 15341671, 2004). "Hypoxia is such a common feature of solid tumours that it is of interest to investigate the expression of Ndrg1 protein in human cancers." (PMID 15341671, 2004).
cancer (continued). "Exploration of Ndrg1 protein expression patterns in various tissues showed that Ndrg1 protein was overexpressed in cancers compared to normal tissues." (PMID 15341671, 2004). "More studies are needed to resolve how Ndrg1 levels are managed in normal cells, during hypoxia, and as well as in cancer cells." (PMID 15341671, 2004). "Additionally, NDRG1-4 are explored as therapeutic targets in oncology, focusing on recent advances in anti-cancer agents that induce the expression of these proteins." (PMID 40378957, 2025). "Furthermore, microarray analysis comparing cancer cells overexpressing NDRG1 to those with normal expression levels revealed that NDRG1 is linked to a network of vesicle transport proteins." (PMID 40332138, 2025). "After identifying NDRG1 as a key gene, we examined its behavior across various cancer types." (PMID 40539245, 2025). "Therefore, NDRG1 inhibits the EMT in cancer cells by downregulating the TGF-β/Smad and WNT/β-catenin signaling pathways." (PMID 40378957, 2025). "This highlights the cancer type-dependent biological effects mediated by NDRG1.Whether the NSUN6-m5C-NDRG1 axis universally drives pan-cancer radioresistance requires." (PMID 40823093, 2025). "The overexpression of NDRG1 is an indicator of poor prognosis in various types of cancer." (PMID 39736699, 2024). "NDRG1, a gene expressed in various tumors, has been reported to have pleiotropic effects in cancer." (PMID 38987777, 2024). "NDRG1 has been shown to potently suppress metastasis in a variety of cancer types." (PMID 39457585, 2024). "N-myc downregulated gene-1 (NDRG1) is known to have diverse roles, functioning both as a suppressor of metastasis and as an indicator of poor prognosis, while also contributing to disease progression across various cancer types." (PMID 39199357, 2024). "The expression at the mRNA and protein levels of NDRG1 could be downregulated by the effect of iron chelators in cancer, highlighting the regulatory role of intracellular iron." (PMID 39457585, 2024). "Moreover, NDRG1 plays a context-dependent role in cancers by either acting as anti- or pro-oncogenic, depending on the cancer type." (PMID 38983911, 2024). "Therefore, NDRG1 can exert contradictory role in cancer depending primarily on the tissue type affected." (PMID 38561462, 2024). "Thus, we further investigated the role of NDRG1 expression in oxygen metabolism in cancer cells using a Seahorse XF96 Analyzer." (PMID 38983911, 2024). "Thus, ABCB1, a key player in drug resistance, and NDRG1, a metastasis suppressor in various cancers, were studied as main targets to improve therapy outcomes." (PMID 39457585, 2024). "Since NDRG1 overexpression may play an important role in inhibiting cancer cell invasion and metastasis, the procurement of the NDRG1 inducer by small molecules may be a promising strategy in the development of anticancer agents." (PMID 37111248, 2023). "The role of N-myc downstream-regulated gene 1 (NDRG1) in human cancer is controversial and remains unclear." (PMID 36594086, 2023). "The activation of mTOR-AKT signaling mediates the progression of NDRG1-related cancer." (PMID 37858101, 2023). "First, NDRG1 has been shown to directly regulate AR signaling in this type of cancer." (PMID 37249826, 2023). "In particular, NDRG1 plays an especial part in controlling PDAC cancer metabolism." (PMID 37249826, 2023). "Given that the loss of phospho-NDRG1 (Thr346) was correlated with an increase in cancer cell apoptosis in response to Torin 2, we hypothesize that phospho-NDRG1 (Thr346) promotes the survival of ccRCC cancer cells." (PMID 37298315, 2023). "TGFβ1 also exhibits a cell-type- and context-dependent pleiotropic effect that promotes or inhibits cancer progression 21; hence, we suggest that this could explain, at least partially, the pleiotropic role of NDRG1." (PMID 36594086, 2023).
cancer (continued). "We hypothesize that phospho-NDRG1 (Thr346) promotes the survival of cancer cells, and thus its targeting could potentially be efficacious for ccRCC." (PMID 37298315, 2023). "Indeed, NDRG1 phosphorylation at Thr346 and Ser330 is a common factor present in multiple cancer types, as well as their localization in cytoplasm and nucleus, respectively 8,10,11." (PMID 36594086, 2023). "Furthermore, several genes whose expression predicts the poor prognosis of many cancer types and represents potential anticancer targets, i.e., Lgals3, Smox, Ndrg1, Neat1, and Rbm39, were significantly upregulated in most of the KO cell types." (PMID 37809094, 2023). "In fact, the effect of NDRG1 on reducing cancer cell TGF-β secretion may lead to fewer myCAFs in the TME, as this CAF sub-type is dependent upon TGF-β signaling." (PMID 37345116, 2023). "However, experiments in a certain type of cancer have sometimes reported opposite effects for NDRG1." (PMID 37249826, 2023). "The anti-apoptotic effect of NDRG1 confers cancer cell resistance to hypoxia and anti-cancer drugs." (PMID 37298315, 2023). "Hence, NDRG1 needs to be further explored and studied to develop into a novel therapeutic agent against cancer." (PMID 37970212, 2023). "Treatments that inhibit RICTOR and mTORC2 reduce phospho-NDRG1 (Thr346) and cancer cell viability." (PMID 37298315, 2023). "The role of NDRG1 in human cancer has sparked controversy, given its dual nature." (PMID 37847564, 2023). "There is limited evidence suggesting NDRG1 can modulate immune cells in the context of cancer." (PMID 37345116, 2023). "Overall, NDRG1 can regulate key molecular pathways that influence cancer cell metabolism." (PMID 37345116, 2023). "ENO1, NDRG1 and NPM1 are reportedly associated with cancer as further discussed." (PMID 38097352, 2023). "NDRG1 protein expression is robustly induced in cancer cells in response to hypoxia." (PMID 37298315, 2023). "Additionally, K-Ras is critical for controlling in vitro NDRG1 protein level in pancreatic ductal adenocarcinoma (PDAC) cancer cells through ERK signaling." (PMID 37249826, 2023). "NDRG1 may act as an oncogene, as it is overexpressed in many types of cancers, including oral, esophageal, gastric, colon, liver, lung, and bladder cancer." (PMID 35563887, 2022). "NDRG1 is poorly understood in cancer due to its context-dependent and pleiotropic functions." (PMID 36497221, 2022). "Since radioresistance and chemoresistance are concurrent presentations of cancer stemness, we examined whether NDRG1 also regulates these functions." (PMID 35563887, 2022). "This function of NDRG1 in augmenting cancer metastasis is also supported by other investigations." (PMID 35563887, 2022). "Cytoplasmic NDRG1 confers cancer stemness and therapeutic resistance." (PMID 35563887, 2022). "N-Myc downstream-regulated 1 (NDRG1) has inconsistent oncogenic functions in various cancers." (PMID 35563887, 2022). "The transcriptomic analysis data indicated that NDRG1 fulfills the attributes of cancer stemness." (PMID 35563887, 2022). "The specific functions of NDRG1 have been examined in a number of cancer types." (PMID 36497221, 2022). "NDRG1 (N-myc downregulated gene-1) has been reported to suppress metastasis, to be a biomarker of poor outcome, and to be a facilitator of disease progression in a range of different cancers." (PMID 36497221, 2022). "Many cancers have been reported to have the N-myc downstream-regulated gene (NDRG1–4) family." (PMID 35795037, 2022). "The collective findings indicated that NDRG1 contributes to cancer stemness and chemo-radioresistance, which may be related to several stemness regulators." (PMID 35563887, 2022). "NDRG1 continues to be an intriguing mediator of cancer progression and metastasis." (PMID 36497221, 2022). "N-myc downregulated gene-1 (NDRG1) has been variably reported as a metastasis suppressor, a biomarker of poor outcome, and a facilitator of disease progression in a range of different cancers." (PMID 36497221, 2022).
cancer (continued). "However, NDRG1 protein is expressed at low levels in normal tissues while NDRG1 mRNA is ubiquitously over-expressed in various human cancers." (PMID 35795037, 2022). "Interestingly, the anti-cancer compounds thiosemicarbazone potently upregulate NDRG1, which both prevents aberrant epithelial-stellate cell crosstalk and synthesis of TN-C." (PMID 35785162, 2022). "NDRG1 offers a wide array of opportunities for cancer treatment owing to its dynamic role." (PMID 36497221, 2022). "Inhibition of NDRG1 has been explored due to its pro-tumourigenic role in some cancer types." (PMID 36497221, 2022). "Moreover, NDRG1, an iron-regulated growth and metastasis suppressor, was negatively correlated with cancer progression in several tumors." (PMID 35053370, 2022). "Despite an upregulation in anergic B cells, N-myc downstream-regulated gene 1 (NDRG1) is not required for the tolerogenic downstream responses, reducing risk of immune modulation on targeting of NDRG1 for cancer therapeutics." (PMID 36357486, 2022). "Our previous studies confirmed the anti-cancer effect of NDRG1 in GC." (PMID 34616614, 2021). "Therefore, it is apparent that NDRG1 functions probably rely on a specific context in different cancer types." (PMID 34965023, 2021). "NDRG1 is considered as a metastasis suppressor in many cancer types." (PMID 35250965, 2021). "Interestingly, the protein expressions of NDRG1 and its downstream anti-cancer signaling are upregulated in OC." (PMID 32550915, 2020). "Our study demonstrated that HIF downstream gene of NDRG1 may counteract the cancer‐promoting effect of HIF." (PMID 32537867, 2020). "NDRG1 has been regarded as a metastasis suppressor in human cancers." (PMID 32099530, 2020). "Furthermore, expression of N-myc downstream regulated gene 1 (NDRG1), a gene that is regulated by hypoxia and cellular proliferation signaling, and can act to both promote and suppress some cancers, has been shown to counteract the function of ATF3." (PMID 33302475, 2020). "Herein, we describe how the expression of a specific protein named N-myc downstream-regulated gene 1 (NDRG1), commonly described as a gene that prevents the spread of cancer cells to distant organs, may have a paradoxical role in cancer progression in IBC." (PMID 33321961, 2020). "However, the status of NDRG1 is also well known to be extremely varying between different carcinoma types." (PMID 32106831, 2020). "In the past decade, interest in NDRG1 as a vital contributor to cancer development has increased." (PMID 30914736, 2019). "In support of these experimental findings, in silico Pearson correlation analysis of human GBM specimens by R2 indicated that NDRG1 expression was anti-correlated to that of ASCL1 in the majority of GBM samples as well as in other different types of cancer (TCGA and PANCANCER datasets)." (PMID 30538287, 2019). "Compounds that activate NDRG1 counter these cancer-promoting E6AP phenotypes." (PMID 31739170, 2019). "Second, to examine whether this novel regulatory mechanism of NDRG1-OT1_v4 exists in other cancer types, similar experiments should be performed in different cancer cell lines and clinical samples." (PMID 29535820, 2018). "Expression of NDRG1 in vivo is dynamic and dependent on microenvironment cues such as hypoxia or iron limitation; nevertheless, in vitro studies represent the most direct approach to examine protein function in cancer cells." (PMID 29898756, 2018). "Hence, our investigation suggests that up-regulation of NDRG1 by DpdtC is a promising therapeutic approach in HER2-overexpressed cancers." (PMID 29467385, 2018). "Moreover, NDRG1 is also reported to have effect on genome stability, apoptosis, even cancer cell stemness." (PMID 29137287, 2017). "Inherent in this postulate is the notion that NDRG1 may be capable of impacting cancer metastasis by more than one mechanism." (PMID 28371345, 2017). "NDRG1 is a potent tumor suppressor gene in multiple types of cancer including CRC." (PMID 29137287, 2017).
cancer (continued). "NDRG1 activation has frequently been found to promote cancer cell chemoresistance." (PMID 28906492, 2017). "CLU, NDRG1, CD166, S100A11 and Galectin-1 were associated with carcinoma and Galectin-3." (PMID 28701735, 2017). "NDRG1 may also have potentially important implications for the diagnosis for osteodystrophy and cancer patients." (PMID 26778110, 2016). "Similar to NDRG1, many studies have implied an anti-cancer role for NDRG237." (PMID 27782193, 2016). "In fact, the expression of one of these molecules, namely N-myc downstream-regulated gene 1 (NDRG1), which is also known as Cap43, could be induced by hypoxia and was negatively correlated with cancer grade and metastasis." (PMID 25860930, 2015). "Epigenetic regulation of NDRG1 expression has been studied in some cancers." (PMID 26692161, 2015). "Together, these observations indicate that NDRG1 promotes the formation of the adherens junction, which is critical for cell–cell adhesion, and elucidates the mechanisms by which this molecule is able to suppress metastasis in cancer cells." (PMID 26431493, 2015). "Previous studies have suggested an important role for NDRG1 expression in numerous types of cancer." (PMID 25777142, 2015). "Thus, each cancer type needs to be evaluated individually for the appropriate intervention based on the specific roles of NDRG1 in that cancer." (PMID 26359353, 2015). "These paradoxical effects of NDRG1 may due to potential post-translational regulation events that have been shown to affect NDRG1 function and could be mediated by genetic alterations that occur in different cancer-types." (PMID 26418878, 2015). "These NDRG1-mediated activities further contribute to decreasing cancer cell migration." (PMID 25860930, 2015). "The 5-year cancer-free survival rate in NDRG1 positive group was 80.89%." (PMID 23874544, 2013). "For instance, high eIF3a levels, which are typical of early cancer stages, increase proliferation (potentially due to low p27kip1 expression) and differentiation, while decreasing migration and invasion (possibly due to high NDRG1 expression)." (PMID 23437357, 2013). "A recent study using cancer cell lines reveals that the tumor metastasis suppressor gene, NDRG1, represses Wnt/β-catenin signaling by directly interacting with the Wnt receptor, LRP6, consequently causing the suppression of Wnt/β-catenin target gene, ATF3 expression." (PMID 23741453, 2013). "While NDRG1 is clearly germane to cellular stress response, cancer, and the function of peripheral neurons, the expression pattern and mechanism of action of NDRG1 remain largely unknown." (PMID 24066183, 2013). "Previous studies have indicated a positive correlation between NDRG1 expression and patient survival, indicating that NDRG1 may be a prognostic biomarker in cancer patients." (PMID 24269992, 2013). "The promoter of NDRG1 contains a large CpG island, raising the possibility that it could be silenced by DNA hypermethylation in cancer." (PMID 23874837, 2013). "The contradictory roles of NDRG1 in cancer remained to be clarified, although they might be explained by its multiple cellular localizations and complex regulation by diverse physiological and pathological factors." (PMID 21912630, 2011). "Overexpression of NDRG1 leads to differentiation of cancer cells." (PMID 17786215, 2007). "Although the precise function of NDRG1 is unknown, there is solid evidence that suggests it may suppress the invasive ability and spontaneous metastasis of cancer cells by inducing differentiation and reversing a metastatic phenotype." (PMID 16832411, 2006). "However, with the exception of the colon samples, the expression of Ndrg1 protein in cancer cells of these tissues was considerably higher." (PMID 15341671, 2004).